ELF3 (E74 like ETS transcription factor 3)
Diseases named in the same sentence as ELF3 in open-access papers (continued):
Sharing a sentence is not in itself a finding about the gene and the disease.
colorectal cancer (15 papers, 2016 to 2023). A primary or metastatic malignant neoplasm that affects the colon or rectum. "ELF3 overexpression is significantly linked to poor outcomes in hepatocellular, colorectal cancer, and lung adenocarcinoma patients, and that ELF3 enhance cell growth, migration in these cancers." (PMID 33742531, 2021). "ELF3 is mutated in 2–4% of gastric cancers (GCs) and colorectal cancers (CRCs), and deleted in a further ~1% of GCs." (PMID 30200227, 2018). "In this study, we decided to focus on the role of ELF3, a transcriptional factor regulating lung epithelial development, which is implicated in airway inflammation and mediates inflammatory signal and tumor progression in prostate cancer and colorectal cancer." (PMID 33144684, 2021). "ELF3 has been identified as carcinogenic in several solid tumours, including lung adenocarcinoma, thyroid cancer, and colorectal cancer 41-43." (PMID 37779866, 2023). "Meanwhile, the reader ELF3 was reported to be closely related to poor survival in colorectal cancer (CRC) patients by driving β-catenin transactivation." (PMID 34291082, 2021). "ELF3 is associated with poor prognosis in different tumor types including LUAD, colorectal cancer, and hepatocellular carcinoma." (PMID 33144684, 2021). "ELF3 is overexpressed in colorectal cancer and promotes colorectal cancer progression by transactivation of β-catenin." (PMID 34771571, 2021). "Western blotting coupled to siRNA as well as analysis of tumour/normal colorectal cancer panels was used to investigate the expression and function of ELF3." (PMID 30148686, 2019). "Knock-down of ELF3 in HCT116 colorectal cancer cells substantially increased ZEB1 expression suggesting that ELF3 functions as a repressor of ZEB1 expression." (PMID 30148686, 2019). "In summary, we have showed using analysis of large-scale gene-expression data and from tumour panels that the expression of ELF3 is consistent with its role as an epithelial marker and tumour suppressor in colorectal cancer." (PMID 30148686, 2019). "ELF3 is overexpressed in colorectal cancer and promotes colorectal cancer cell proliferation and invasion by enhancing β-catenin signaling." (PMID 29523781, 2018). "In colorectal cancer, knockdown of ELF3 in HCT116 cells induced ZEB1 upregulation." (PMID 36864480, 2023). "ELF3 overexpression is involved in the metastasis process in non-small cell lung cancer and its expression can be a useful biomarker of lymph node metastasis in colorectal cancer, while IFI6 promotes metastasis in breast cancer cells." (PMID 30939818, 2019). "Analysis of gene-expression patterns across The Cancer Genome Atlas (TCGA) and protein localization in colorectal cancer tumour panels showed that ELF3 expression is anti-correlated with β-catenin and markers of EMT and correlates with better clinical prognosis." (PMID 30148686, 2019). "The regulation of JMJD2B in a HIF-1α-dependent manner during hypoxia increases the invasiveness of colorectal cancer cells by reducing the levels of the repressive mark H3K9me3 in genes like ELF3 (E74-like ETS transcription factor 3) and IFI6 (Interferon Alpha Inducible Protein 6)." (PMID 30939818, 2019). "However, the trend was reversed in colorectal cancer, where high ELF3 levels correlated with better patient prognosis in terms of overall survival, relapse-free survival and metastasis-free survival (GSE16125, GSE39582, GSE28814 and GSE28722), similar to reports in ovarian and bladder cancer." (PMID 36864480, 2023). "Transcriptomic analysis of mutant and wild-type β-catenin colorectal cancer cells showed that mutant cells were enriched with mesenchymal markers such as Vimentin (VIM) and that ELF3 was significantly more abundant in wild-type β-catenin cells." (PMID 30148686, 2019). "In this study we identified ELF3 as a repressor of the EMT-TF and marker ZEB1 in colorectal cancer cells through its antagonism of Wnt and RAS oncogenic signalling pathways." (PMID 30148686, 2019).
prostate carcinoma (14 papers, 2010 to 2025). A carcinoma that arises from epithelial cells of the prostate gland. "Collectively, these findings suggest that loss of ELF3 represents an additional means of enhancing AR activity in prostate cancer cells." (PMID 30200227, 2018). "ELF3 is an interaction partner with NFKB in prostate cancer cells in response to pro-inflammatory stimuli, a pathway that also impacts myometrial cells." (PMID 40455848, 2025). "Next, we interrogated ELF3 levels in LNCaP prostate cancer cells along the EMT trajectory upon SNAIL induction and a subsequent MET over 20 days after withdrawal of SNAIL induction." (PMID 36864480, 2023). "This study indicates that ELF3 functions not only as a part of normal prostate epithelial growth but also as a potential oncogene in advanced prostate cancers." (PMID 35472129, 2022). "ELF3 induces breast epithelial cell malignant transformation, and promotes prostate cancer progression by interacting with NFκB." (PMID 33618713, 2021). "Through NF-κB, IL-1β induces the activation of epithelium-specific ETS (E26 transformation-specific) ESE1 (or E74-like factor (ELF3)), two ETS family members responsible for prostate cancer malignancy and associated with a poor prognosis for patients." (PMID 32635472, 2020). "While they did identify a subset of prostate cancers with increased ELF3 mRNA expression, they observed downregulation of ELF3 mRNA in the majority of primary tumours." (PMID 30200227, 2018). "The high ELF3 expression in prostate cancers is driven, at least in part, by the pro-inflammatory cytokine IL-1β, in a NF-κB-dependent manner." (PMID 30200227, 2018). "In turn, ELF3 interacts with NF-κB and enhances NF-κB-driven transcription, creating a positive feedback loop which constitutively activates NF-κB and promotes prostate cancer progression." (PMID 30200227, 2018). "ELF3 mRNA and protein expression are increased in primary prostate cancers compared to normal prostate tissue, and further increased in metastases." (PMID 30200227, 2018). "Further to this, stable expression of ELF3 in LNCaP and 22RV1 prostate cancer cells increased proliferation, colony formation, cell migration and resistance to anoikis in vitro, and promoted formation of lung metastases in vivo." (PMID 30200227, 2018). "ELF3 activates NF-kB signalling pathway and drives prostate cancer." (PMID 40996711, 2025). "In recent years, ELF3 has been frequently thought as a regulator for cell cycle and epithelial differentiation to participate in the development of several cancers such as oral squamous cell carcinoma, non-small cell lung cancer and prostate cancer [28, -30]." (PMID 39572025, 2024). "In prostate cancer, ELF3 regulates the NF-κB pathway after stimulated by inflammatory signals, suggesting that it may connect the TME signals and tumor progression." (PMID 33144684, 2021). "Notably, the subset of prostate cancers which express high levels of both ELF3 and nuclear NF-κB (p65) have a significantly worse prognosis." (PMID 30200227, 2018). "Besides the critical roles of ELF3 in epithelial cell differentiation, gut development, inflammation, and apoptosis, it is also essential for the pathophysiology of cancer epithelial cells such as in breast, lung and prostate cancers." (PMID 31404945, 2019). "Silencing ELF3 in both benign prostate (BPH‐1) and prostate cancer (PC3) cell lines resulted in decreased colony‐forming ability, inhibition of cell migration and reduced cell viability due to cell cycle arrest, establishing ELF3 as a cell cycle regulator." (PMID 35472129, 2022). "This study aimed to elucidate the role of ELF3, an ETS family member in normal prostate growth and prostate cancer." (PMID 35472129, 2022).
lung carcinoma (13 papers, 2012 to 2026). "This study revealed that overexpression of ELF3 in the PTEN-deficient lung epithelium promoted lung cancer development by inhibiting ferroptosis." (PMID 39695109, 2024). "Consistent with the previous results, cell colonies were significantly increased by ELF3 overexpression under PTEN-deficient background either in lung cancer cells H1650 or in lung epithelial cells NL20." (PMID 39695109, 2024). "In summary, our findings revealed that overexpression of ELF3 in the PTEN-deficient lung epithelium promoted lung cancer development by inhibiting ferroptosis partially through the directly induced expression of SLC7A11." (PMID 39695109, 2024). "We then conducted similar experiments in vivo using xenograft models and observed that erastin specifically and significantly attenuated the development of lung cancer with the ELF3 overexpression and the PTEN-deficient background." (PMID 39695109, 2024). "In our study, we found that ANF effectively represses the PKCί–ELF3 axis and inhibits tumor growth of lung cancer cells harboring EGFR mutation relevant to 1st-generation EGFR TKI resistance." (PMID 34830169, 2021). "To decipher the mechanisms underlying the role of ELF3 overexpression in promoting lung cancer development under the PTEN-deficient human and murine lung epithelium, we performed RNA-Seq analysis to identify the DEGs between 12-month-old ELF3OV/+Ptend/d and Ptend/d mouse lungs." (PMID 39695109, 2024). "Importantly, targeting SLC7A11 using its inhibitor, erastin, showed obvious inhibition on the colony formation of lung cancer cells and cancer development with ELF3 overexpression and PTEN deficiency by inducing ferroptosis." (PMID 39695109, 2024). "Interestingly, the low mutation rate of ELF3 in lung cancer has allowed it to elude sequencing-based screens of recurrently altered oncogenes; the high frequency of alternative DNA-level disruptions in upwards of 80% of LUAD underscores the importance of interrogating multiple ‘omics' levels." (PMID 31780666, 2019). "For example, ELF3 promotes tumor development in breast, prostate, and lung cancers, whereas it suppresses tumorigenesis in bladder and oral squamous cancers." (PMID 41498327, 2026). "In lung cancer cells harboring K-ras mutations and EGFR L858R/T790M mutations, the knockdown of ELF3 significantly increases cell apoptosis." (PMID 40429988, 2025). "Here, we showed that the synergistic role of ELF3 overexpression and PTEN deficiency in driving lung cancer development was highly dependent on the regulation of ferroptosis." (PMID 39695109, 2024). "In this study, using genetically modified mice, we specifically overexpressed hELF3 in mouse lung epithelium by generating genetic mouse models and investigated the in vivo role of ELF3 in lung cancer development." (PMID 39695109, 2024). "By integrating the clinical analyses and genetic mouse models, we found that ELF3 overexpression in the PTEN-deficient background promoted cell proliferation and inhibited ferroptosis by inducing SLC7A11 expression, thus promoting lung cancer development." (PMID 39695109, 2024). "Mouse-derived Elf3 was found to be up-regulated with mouse lung cancer development in our previous article published in 2015, suggesting its pro-carcinogenic role." (PMID 39695109, 2024). "And then, ELF3 overexpression in lung cancer cells was found to promote cell growth and metastasis through PI3K/AKT and ERK signaling pathways." (PMID 39695109, 2024). "Although single overexpression of hELF3 in murine lung epithelium did not induce lung tumor development, the elevated expression of ELF3 in human lung tumors suggests its potential role in lung cancer development." (PMID 39695109, 2024). "Taken together, ELF3 overexpression and PTEN deficiency in human and murine lung epithelium synergistically facilitate lung cancer development." (PMID 39695109, 2024). "ELF3 and SLC7A11 expression levels were negatively associated with lung cancer patients’ survival rates." (PMID 39695109, 2024).
lung carcinoma (continued). "Expression profiling analysis in human lung tumors has confirmed the importance of the ErbB2/Akt/ELF3 signaling pathway as a prognostic biomarker and therapeutic drug target for lung cancer treatment." (PMID 37990309, 2023). "To assess the relevance of the ELF3 gene in lung cancer, we analyzed the aberrant status of ELF3 in the TCGA Firehose Legacy LUAD dataset (n = 586)." (PMID 34830169, 2021). "Of note, ELF3 becomes inactivated in lung cancer cells, which is consistent with its role in lung epithelial cell differentiation being impaired in cancer." (PMID 33083012, 2020). "Here, we show that ELF3 is an oncogene in the adenocarcinoma subtype of lung cancer (LUAD), providing genetic, functional, and clinical evidence of subtype specificity." (PMID 31780666, 2019). "ELF3 is tumor suppressive in many cancers of epithelial origin but in lung cancer, the authors describe an oncogenic role in the adenocarcinoma histology of non-small cell lung cancer." (PMID 31780666, 2019). "Additionally, ELF3 mRNA expression was still negatively correlated with the survival of lung cancer patients with low expression of PTEN." (PMID 39695109, 2024). "Interestingly, the largest ELF3-related network was identified in lung cancer, more specifically LUAD." (PMID 31780666, 2019). "Conversely, overexpression of EHF drives HER2 expression in gastric and thyroid cancers, sensitizing these tumours to HER2 inhibition, while in lung cancer cell lines, ELF3 overexpression activates the PI3K/AKT and MAPK pathways and sensitized lung cancer cells to inhibitors of these pathways." (PMID 30200227, 2018). "Hitherto, there is no report describing the association of ELF3 expression and metastasis of lung cancer." (PMID 27827952, 2016). "However, the additional functions of ELF3 in various kinds of tumors have frequently been studied for many years since its expression in lung cancer tissues and lung cancer cell lines was first discovered in 1997." (PMID 27827952, 2016). "Furthermore, both cellular and xenograft studies showed ELF3 as an oncogene in lung cancer." (PMID 39695109, 2024). "Therefore, to assess the effect of ELF3 on lung cancer cell survival, we knocked down the expression of ELF3 by transfecting ELF3 siRNA into A549 (with K-Ras mutation) and H1975 (with EGFR L858R/T790M double mutation) lung cancer cells for 72 h." (PMID 34830169, 2021). "ELF3 is an important factor associated with cell survival of lung cancer cells, and ANF is a potent inhibitor that represses cell growth and induces apoptosis of lung cancer cells through downregulation of the PKCί–ELF3 axis in K-Ras mutant A549 lung cancer cells." (PMID 34830169, 2021). "These differential effects were also seen in human lung cancer cells with PTEN-null background and ELF3 overexpression." (PMID 39695109, 2024). "Therefore, we counted the proportion of lung cancer patients with low expression of PTEN and high expression of ELF3 as a percentage of all lung adenocarcinoma patients recorded in two databases, which were 27.3 and 29%, respectively." (PMID 39695109, 2024). "To explore the function of ELF3 in lung cancer, we examined its protein expression in several lung cancer cell lines and found that ELF3 was detectable in most of the cell lines regardless of the mutational status of EGFR or K-RAS." (PMID 34830169, 2021). "Furthermore, functional studies demonstrated that ELF3 knockdown inhibited proliferation, metastasis and EMT of lung cancer cell lines, and inhibited PI3K/AKT and ERK signalling, suggesting a tumour promoting role in these cancers." (PMID 30200227, 2018). "Interestingly, the top 5 most highly expressed SAE-enriched transcription factors all have previously been established as having a role in airway biology and/or lung cancer, including FOXJ1, ELF3, TRIM29, SOX2, and FOXA1." (PMID 22375630, 2012).
lung carcinoma (continued). "To investigate the reason that ELF3 overexpression failed to induce the formation of lung tumors even though it has been reported to be a potential oncogene in human lung cancer cells and xenograft models, we conducted the transcriptome analysis of mouse lungs with ELF3 overexpression using RNA-Seq." (PMID 39695109, 2024). "Consistently, we observed the positive correlation between ELF3 and SLC7A11 expression only in human lung cancer tumors with the PTEN low expression, not in the whole patient population." (PMID 39695109, 2024). "Here we observed ELF3 activation in the lung non-ciliated cells from smokers and overexpression in bulk LUSC tissue, but inactivation in single lung cancer cells (predominantly LUAD) and no expression change in bulk-tissue LUAD." (PMID 33083012, 2020).